HSPB8 (heat shock protein family B (small) member 8)
Diseases named in the same sentence as HSPB8 in open-access papers (continued):
Sharing a sentence is not in itself a finding about the gene and the disease.
distal myopathy (6 papers, 2017 to 2023). Distal myopathy refers to a group of muscle diseases which share the clinical pattern of predominant weakness and atrophy beginning in the feet and/or hands. "A unique autosomal dominant rimmed vacuolar myopathy, caused mainly by frameshift mutations of the HSPB8 gene, is associated with a distal myopathy that leads to progressive generalised weakness." (PMID 37462824, 2023). "Accordingly, mutation or deficiency in p62, BAG3, and HSPB8 has been shown to induce distal myopathy associated with rimmed vacuole and myofibrillar disorganisation on muscle biopsy." (PMID 28780615, 2018). "More recently, the disease spectrum caused by mutations in HSPB8 was expanded to distal myopathy." (PMID 32323160, 2020). "Altogether, our results lead us to conclude that the accumulation of mutant Hspb8K141N combined with an inability to degrade Hspb8-positive aggregates through Hspb8/Bag3-mediated autophagy is a key pathomechanism underlying the peripheral neuropathy and distal myopathy in our mouse model." (PMID 28780615, 2018). "In addition, abnormalities of some HSPB members are involved in muscle disorders: HSPB5 mutations are associated with myofibrillar myopathies and HSPB1 or HSPB8 to distal myopathy and Charcot–Mary–Tooth disease type 2." (PMID 29316663, 2018). "Moreover, it was recently demonstrated that some patients with HSPB1 and HSPB8 mutations may have rare forms of ALS or distal myopathy, respectively, further supporting the genetic and clinical heterogeneity." (PMID 32323160, 2020). "It is the first report of an Hspb8 transgenic mouse line modelling distal myopathy and the faithful reproduction of a human hereditary neuromuscular disease phenotype by a mouse model is actually a rather rare event." (PMID 28780615, 2018). "Heat shock protein HSPB8 also known as HSP22 (22 kDa) is a cytoplasmic protein that serves as a member of the chaperone‐assisted autophagy complex and is involved in Charcot‐Marie‐Tooth disease type 2L as well as in a rare form of human distal myopathy." (PMID 33403800, 2021).
glioblastoma (6 papers, 2012 to 2023). The most malignant astrocytic tumor (WHO grade IV). "High levels of HSPB8 mRNA were observed in U87 glioblastoma cells, in which the HSPB8 protein inhibits Sam68 (also named GAP-associated tyrosine phosphoprotein p62)." (PMID 33562660, 2021).
Charcot-Marie-Tooth disease (5 papers, 2006 to 2021). An inherited degenerative disorder involving the peripheral nerves. "Partial evidence for haploinsufficiency has also been provided for HSPB8 mutants, which have lost the HSPB8 chaperone-like activity to deal with aggregation-prone polyQ proteins, resulting in Charcot-Marie-Tooth disease." (PMID 24719117, 2014).
lung adenocarcinoma (5 papers, 2021 to 2025). A carcinoma that arises from the lung and is characterized by the presence of malignant glandular epithelial cells. "HSPB8 suppressed mitochondrial impairment and aggravated proliferation and migration of A549 lung adenocarcinoma cells." (PMID 37404760, 2023).
myeloma (5 papers, 2014 to 2022). "Myeloma research has linked HSPB8 levels and resistance to proteasome inhibitors." (PMID 33562660, 2021). "For example, in myeloma cells, HSPB8 is robustly overexpressed in Velcade-resistant cells, where it confers a selective resistance to the drug." (PMID 33562660, 2021). "Hence, high levels of HSPB8 in myeloma represent a factor of cell survival and resistance to therapy." (PMID 33562660, 2021). "In conclusion, the results presented herein suggest that overexpression of HSPB8 in myeloma cells could play an important role for the elimination of cell aggregates in velcade-resistant cells that therefore contributes to their enhanced survival." (PMID 25051369, 2014). "Although increased autophagy, mediated by increased HSPB8 expression, has recently been demonstrated to be involved in BTZ resistance in multiple myeloma cells, we found no increased activity of this pathway in BTZ-resistant CEM cells." (PMID 27542283, 2016). "In agreement with the gene model, compared with bortezomib-sensitive myeloma cell lines (negative control), there was an increase in mRNA expression of SCN9A, RGS7, NTF3, HSPB8, and ZBED1 and a decrease in CCND1, COBLL1, EGR1, OCLN, and ZBED1 mRNA expression of bortezomib-resistant cell lines." (PMID 36467498, 2022).
atherosclerosis (4 papers, 2022 to 2025). A disease characterized by the build-up of fatty material and calcium deposition in the arterial wall resulting in partial or complete occlusion of the arterial lumen. "At present, investigations into the function of HSPB8 in atherosclerosis are scarce, and the underlying mechanisms through which HSPB8 may impact atherosclerosis are yet to be determined." (PMID 41031220, 2025). "In summary, BAG3 mitigates atherosclerosis by suppressing EndMT via synthesizing a CASA complex with HSP70 and HSPB8 to activate autophagy." (PMID 35893075, 2022).
diabetes (4 papers, 2014 to 2025). "GLUT4 interacting proteins, such as MDH and the stress proteins HSPB8 and GRP78, exhibited decreased expression when D animals were exposed to F. The presence of the two stress proteins indicates an increase in IR, which might worsen diabetes." (PMID 25180703, 2014).
hepatocellular carcinoma (4 papers, 2017 to 2023). A malignant tumor that arises from hepatocytes. "Moreover, HSPB8 downregulation in a typical hepatoma cell line, HuH-7, caused a marked increase in cell migration induced by TGF alpha." (PMID 33562660, 2021).
Huntington disease (4 papers, 2014 to 2025). Huntington disease (HD) is a rare neurodegenerative disorder of the central nervous system characterized by unwanted choreatic movements, behavioral and psychiatric disturbances and dementia. "Additionally, increased HSPB8 expression prevents aggregation of the mutant huntingtin protein (Htt43Q), a pathogenic factor in Huntington’s disease." (PMID 40385290, 2025). "Remarkably, post-mortem analyses of brain tissue from patients with Alzheimer disease, Parkinson disease, Huntington disease, and spinocerebellar ataxia type 3 (SCA3) have revealed increased HSPB8 and BAG3 expression in astrocytes within affected cerebral areas." (PMID 40385290, 2025).
ischemia (4 papers, 2017 to 2021). A hypoperfusion of the BLOOD through an organ or tissue caused by a PATHOLOGIC CONSTRICTION or obstruction of its BLOOD VESSELS, or an absence of BLOOD CIRCULATION. "Hspb8, also named heat shock protein 22/H11 Kinase (Hsp22), is the stress-inducible small heat shock protein responsive to various conditions of myocardial stress, including ischemia." (PMID 29212219, 2017). "HSPB8/HSP22 is another small HSP whose expression is swiftly induced after ischemia." (PMID 29615920, 2018).
lung carcinoma (4 papers, 2021 to 2025). "HSPB8 is a stress-related protein that plays an important role in tumor proliferation, invasion and apoptosis in lung cancer." (PMID 37291533, 2023).
bladder cancer (3 papers, 2022 to 2024). "To elucidate the functional significance of HSPB8 in bladder cancer (BCa), we generated HSPB8 knockdown cell models." (PMID 38213722, 2024). "Collectively, these findings underscore the pivotal role of HSPB8 in regulating the proliferation and migration of bladder cancer cells." (PMID 38213722, 2024). "To elucidate the clinical significance of HSPB8 in bladder cancer tissues, we conducted immunohistochemical staining on 68 bladder cancer tissue samples and 40 adjacent normal tissue specimens." (PMID 38213722, 2024). "According to RNA-seq results from The Cancer Genome Atlas (TCGA), bladder cancer tissues with positive lymph nodes showed significantly elevated HSPB8 expression." (PMID 38213722, 2024). "Post-lentiviral transduction, we assessed the impact of HSPB8 on bladder cancer cell proliferation utilizing the Celigo cell counting assay, transwell migration assay, and wound-healing assay." (PMID 38213722, 2024). "In conclusion, our findings suggest that HSPB8 plays a potential role in the onset and progression of bladder cancer." (PMID 38213722, 2024). "Another study explored HSPB8 expression in bladder cancer and found that its mRNA expression in bladder cancer was lower than in normal epithelial tissues 8, which appears inconsistent with our findings." (PMID 38213722, 2024). "To explore the potential impact of HSPB8 on the prognosis of bladder cancer patients, we utilized the PanCanSurvPlot 9 online tool to conduct survival analyses on tissue samples from both TCGA and GEO databases." (PMID 38213722, 2024). "Furthermore, our statistical analysis across multiple public database datasets revealed a significant association between high HSPB8 expression and poorer prognosis in various cancers, including bladder cancer, suggesting HSPB8's potential oncogenic function." (PMID 38213722, 2024). "Furthermore, immune cell infiltrate analysis indicated B cells, CD4+T cells, and CD8+T cells were significantly different across high HSPB8 expression group and low HSPB8 expression group in bladder cancer." (PMID 37404760, 2023). "Similarly, higher clinical stages of bladder cancer also displayed augmented HSPB8 expression." (PMID 38213722, 2024). "However, the functional and clinicopathological significance of HSPB8 expression in bladder cancer (BC) remains unclear." (PMID 35330734, 2022).
cognitive decline (3 papers, 2021 to 2023). "Next, due to the important role of oxidative stress (OS) in the T2DM-related cognitive decline, we explored the role of HSPB8 on OS." (PMID 35958024, 2022). "HSPB8 overexpression reversed described levels for cognitive decline." (PMID 35958024, 2022). "Overexpression of HSPB8 relieved cognitive decline in DM mice." (PMID 35958024, 2022). "This study suggests that HSPB8 could be a promising therapeutic target for T2DM-related cognitive decline." (PMID 35958024, 2022). "Due to the vital role of mitochondria homeostasis in the T2DM-related cognitive decline, it is vital to explore whether overexpression of HSPB8 could ameliorate mitochondrial dysfunction in the brains of the T2DM mouse model." (PMID 35958024, 2022). "Overexpression of HSPB8 might be a useful strategy for treating T2DM-related cognitive decline." (PMID 35958024, 2022).
Cognitive impairment (3 papers, 2020 to 2023). Abnormal cognition is characterized by deficits in thinking, reasoning, or remembering. "HSPB8 overexpression helped to mediate the oxidative stress system and improved cognitive impairment." (PMID 35958024, 2022). "The current study demonstrated that overexpression of HSPB8 exacted protective effects, which in turn ameliorated the excessive mitochondrial fission, aggravated neuroinflammation, reduced oxidative stress, and ultimately relieved cognitive impairments." (PMID 35958024, 2022). "Overexpressing HSPB8 in the hippocampi inhibited NLRP3 inflammasome activation via dephosphorylating DRP1 at the phosphorylated site Ser616 (p-Drp1S616), reduced oxidative stress, and ultimately relieved cognitive impairments." (PMID 35958024, 2022). "Overexpressing HSPB8 in the hippocampi could inhibit NLRP3 inflammasome activation via regulation of Drp1 phosphorylation (p-Drp1S616), reduce oxidative stress, and relieve cognitive impairments in diabetic mice." (PMID 35958024, 2022). "Moreover, taking account of the HspB8 results, these findings suggest that the cell‐type specific dysregulation of clusterin distinguishes between individuals with or without cognitive deficits and is specific to clusterin and not simply reflecting an underlying reactive process." (PMID 31386770, 2020). "However, HspB8, while statistically significantly upregulated in the white matter glia of ALS cases with TDP‐43 pathology compared to non‐neurological controls, unlike clusterin, was not differentially regulated between individuals with or without cognitive deficits." (PMID 31386770, 2020).
leukemia (3 papers, 2021 to 2022). A malignant (clonal) hematologic disorder, involving hematopoietic stem cells and characterized by the presence of primitive or atypical myeloid or lymphoid cells in the bone marrow and the blood. "HSPB8 is expressed at low levels also in a hematologic tumor cell line and bone marrow samples from patients with leukemia." (PMID 33562660, 2021). "Thus, HSPB8 expression levels can be seen as a biomarker in following the use of 5-Aza-cytidine in leukemias and lymphoma." (PMID 33562660, 2021).
muscular dystrophy (3 papers, 2017 to 2025). Muscular dystrophy (MD) refers to a group of more than 30 genetic diseases characterized by progressive weakness and degeneration of the skeletal muscles that control movement. "Patients’ muscle biopsy showed muscular dystrophy patterns with inclusions and rimmed vacuoles, consistent with findings in HSPB8-associated (neuro)myopathy." (PMID 40467930, 2025).
myocardial infarction (3 papers, 2017 to 2023). Gross necrosis of the myocardium, as a result of interruption of the blood supply to the area, as in coronary thrombosis. "After myocardial infarction, HSPB8 translocates to the mitochondrial inner membrane in rat hearts." (PMID 36979812, 2023).
myocardial ischemia (3 papers, 2017 to 2024). A disorder of cardiac function caused by insufficient blood flow to the muscle tissue of the heart. "The HSPB family contains HSPB8, which participates in diverse pathological processes, such as neurological diseases 19, 20, myocardial ischemia 21, cancers 22-24, and autoimmune diseases." (PMID 38213722, 2024). "Cardiac-specific overexpression of Hspb8 in a transgenic mouse provides protection against myocardial ischemia that is equally powerful to ischemic preconditioning through the induction of the inducible isoform of nitric oxide synthase (iNOS)." (PMID 29212219, 2017). "In addition, HSPB8 is cardioprotective in experimental models of myocardial ischemia." (PMID 28484965, 2017).
myofibrillar myopathy (3 papers, 2017 to 2020). "In line with human patients with HSPB8-related myopathy, the muscle pathology shows features of human myofibrillar myopathy, with Z-disc disintegration, accumulation of granulofilamentous material, aggregates positive for HSPB8, CRYAB, and desmin, and rimmed vacuoles." (PMID 32093037, 2020). "Myofibrillar myopathy (MFM) is also caused by aggregation-prone mutations in proteins associated with the Z-disc, including αB-crystallin, SQSTM1, and BAG3, which interact with HSPB8 to mediate chaperone-assisted-selective autophagy (CASA), a process required for the maintenance of myofibrils." (PMID 28780615, 2018).
neuroblastoma (3 papers, 2016 to 2020). Neuroblastoma (NB) is the most common solid, extracranial childhood tumor. "As such, the aims of the present study were to explore the relationship between mutant HSPB8 and mitochondria, in addition to investigating the protective effect of NBP against HSPB8 K141N mutation caused neurotoxicity in cultured neuroblastoma SH-SY5Y cells." (PMID 28747872, 2017). "Another member of the small heat shock protein family, Hsp22/HspB8, was shown to be expressed on the surface of human neuroblastoma SK-N-SH cells." (PMID 32443761, 2020). "The results have shown that only colchicine and doxorubicin were able to robustly upregulate the expression of the endogenous human HSPB8 in neuroblastoma cells." (PMID 26961006, 2016). "To further verify our results, we used neuroblastoma SH-SY5Y cells transfected with WT and K141N HSPB8." (PMID 28747872, 2017).
osteosarcoma (3 papers, 2020 to 2024). A usually aggressive malignant bone-forming mesenchymal neoplasm, predominantly affecting adolescents and young adults. "HSPB8/RHD/AASS/NFASC has not yet been found to be associated with osteosarcoma." (PMID 36983630, 2023). "HSPB8, RHD, AASS, and NFASC were genes we identified that have not been previously reported to be associated with osteosarcoma." (PMID 36983630, 2023). "To date, there are no studies combining HSPB8 and human osteosarcoma." (PMID 36983630, 2023).
Spinocerebellar ataxia type 3 (3 papers, 2014 to 2025). "Moreover, we employed the Josephin domain of the ataxin‐3, the poly‐Q containing protein responsible for the spinocerebellar ataxia Type 3, as an amyloid protein model to study the chaperone‐like activity of HspB8 alone and in the HspB8‐BAG3 complex." (PMID 37243950, 2023). "In this complex scenario, at first we demonstrated the capability of HspB8 to inhibit the aggregation of the Josephin domain, the structured part of the ataxin‐3 protein (ATX3) that triggers the earliest steps of the expanded ATX3 fibrillation and the onset of the Spinocerebellar Ataxia type 3." (PMID 37243950, 2023).
triple-negative breast carcinoma (3 papers, 2023 to 2025). An invasive breast carcinoma which is negative for expression of estrogen receptor (ER), progesterone receptor (PR), and human epidermal growth factor receptor 2 (HER2). "Recent evidence has shown that HSPB8, upregulated in hyperthermia-treated triple-negative breast cancer (TNBC) cells, can be transferred via exosomes into THP-1 cells and modulate macrophage polarization." (PMID 40700132, 2025). "In addition, thermotherapy can promote macrophage M1 polarization in the immune microenvironment of triple-negative breast cancer tumors through exosome-mediated HSPB8 transfer." (PMID 39006030, 2024).
cerebral amyloid angiopathy (2 papers, 2018 to 2021). "The low-activity chaperones HspB2, HspB6 and HspB8 specifically associate with fibrillar amyloid β rather than non-aggregated forms in a hereditary cerebral amyloid angiopathy caused by the rapidly aggregating amyloid β1–40 carrying the “Dutch” mutation 22Glu → Gln." (PMID 29969581, 2018).
colorectal cancer (2 papers, 2023 to 2024). A primary or metastatic malignant neoplasm that affects the colon or rectum. "RBBP4 can deacetylate histones in the HSPB8 promoter region and inhibit HSPB8 transcription, thereby promoting the proliferation and invasion of colorectal cancer cells." (PMID 37907984, 2023).
distal hereditary motor neuropathy type 2 (2 papers, 2021 to 2024). "Distal Hereditary Motor Neuropathy type 2 can be caused by any of four genes: HSPB8, HSPB1, HSPB3, or FBXO38 and affects fewer than one in a million people." (PMID 39480826, 2024).
distal motor neuropathy (2 papers, 2014 to 2025). "In this context, inactivating HSPB8 mutations (K141E, K141N) were described to cause distal motor neuropathy." (PMID 25051369, 2014).
motor neuron diseases (2 papers, 2016 to 2024). "Finally, HSPB8 mutations (K141E and K141N) have been associated with motor neurone diseases, further strengthening the hypothesis that alteration of HSPB8 function could have a significant impact on motor neurone viability and that its potentiation/upregulation could help protect against disease." (PMID 27466192, 2016). "Interestingly, missense mutations in the human orthologues of two closely related small heat shock proteins, HspB8 (Hsp22) and HspB1 (Hsp27), are known to form abnormally strong interactions with GEM3 that are associated with motor neuron diseases." (PMID 39492846, 2024).
muscle disorders (2 papers, 2017 to 2018). "Conversely, mutations in small HSPs such as HSPB1, HSPB3, HSPB5, HSPB8 and the co-chaperones DNAJB6 and BAG3 have all been associated with motor neuron and muscular diseases." (PMID 28396624, 2017).
rheumatoid arthritis (2 papers, 2021). A chronic, systemic autoimmune disorder characterized by inflammation in the synovial membranes and articular surfaces. "Roelofs and colleagues analyzed the involvement of HSPB8 in the pathogenesis of rheumatoid arthritis (RA), showing that HSPB8 could induce monocyte-derived dendritic cell maturation and cytokine production in a TLR4-dependant way." (PMID 33562660, 2021).